C4B (complement C4B (Chido/Rodgers blood group))
Diseases named in the same sentence as C4B in open-access papers (continued):
Sharing a sentence is not in itself a finding about the gene and the disease.
tumor (38 papers, 2014 to 2025). "Within the macrophages, we identified two clusters of tumor-associated macrophages (TAMs; Fcgr2b+, Ccl4+, Trem2+) and one enriched in complement genes (C4b+, Cfp+, C1qb+)." (PMID 38570533, 2024). "As a complement regulatory protein, CD46 prevents complement membrane attack complex (MAC) formation by degrading C3b/C4b, thereby protecting tumor cells from complement-mediated lysis." (PMID 41415031, 2025). "In our multiplex studies of isolated tumor tissue, the mouse complement C4 (C4b) gene was detected as one of the most upregulated genes/proteins with all three methods (NGS, Nanostring, MS)." (PMID 33917524, 2021). "C4b mRNA was measurable by qPCR from in vitro 4T1 cell culture, demonstrating that 4T1 tumor cells produce C4b." (PMID 33917524, 2021). "The most common MMP in this group, membrane type 1 MMP (MT1-MMP), interferes with the hosts' immune system by inactivating C3b and C4b and removing them from the cell surface of tumour cells." (PMID 24800085, 2014). "In addition, multiple components of the complement system, a central mediator of RT-induced tumor-specific immunity, were upregulated — specifically, C1qa, C1qb, C1ra, C1s1, C3, C3ar1, C4b, and C6." (PMID 37345658, 2023). "Complement activation via the classical pathway, besides the formation of the membrane-attack complex which mediates direct target cell lysis, also may increase the sensitivity of opsonized tumor cells (C3b and C4b) for phagocytosis by myeloid cells." (PMID 36119088, 2022). "On the other hand, C3b or C4b opsonized tumor cells may be sensitized for phagocytic activity of macrophages and myeloid cells by engagement of complement receptors." (PMID 36119088, 2022). "Consistently, the features for suppression of anti-tumor immunity were dominantly elevated in the CDC20-high group, such as BTLA, CTLA4, CD4, ITGAM, C4B, CD163, and CD206." (PMID 37528490, 2023). "Eight proteins were significantly varied only based on the KW tests, showing variations among the three groups and including three proteins never detected in D tumor samples, two proteins never detected in S tumor samples, and one protein (complement C4-B) never detected in either S or H samples." (PMID 39195201, 2024).
infection (18 papers, 2009 to 2025). The state of being infected such as from the introduction of a foreign agent such as serum, vaccine, antigenic substance or organism. "Infection with WNV induced expression of serum proteins associated with acute phase responses and inflammatory processes including complement pathway proteins C4B, and kallikrein (KLKB1), both of which are involved in complement activation." (PMID 36569838, 2022). "We recently found that OspC, by binding the complement component C4b, promotes bloodstream survival at early stages of infection." (PMID 32413091, 2020). "In EBOV-infected NHPs, C4B levels were actually reduced 1.3 fold from the pre-infection level (ratio = 0.75) on Day 6 PI." (PMID 30774579, 2019). "Next, we investigated the mechanism by which C4b deposition on the Ad5 capsid interferes with infection." (PMID 30926239, 2019). "The C3L gene codes for a secreted complementbinding protein(CBP) in infected cells at the early stage of infection and inactivates complement through interaction with C3band C4b." (PMID 26798498, 2015). "Despite low titers of C4A and C4B during acute single strain infection, viral titers in the salivary gland of C4A and C4B singly infected mice at day 18 p.i. were not significantly different to those detected in C4C or C4D infected mice." (PMID 23300458, 2013). "Infectious virus was undetectable in the spleens of C4A inoculated mice 3 days after infection, while titers of virus in C4B infected mice were just above the limit of detection." (PMID 23300458, 2013). "The C4 cleavage product, C4b (α,β,γ, chains), resulting from both of the reactions only emerged under infection-inflammation condition." (PMID 19180241, 2009). "Analysis of the vessel data revealed several proteins related to the acute-phase response to infection (Hp, Hpx, Serpina3n, Fga/b, Igfbp7, Cfh, and C4b), antigen presentation (Tap1, Tap2, Tapbp, H2-D1, and H2-Q10), and interferon response (Igtp, Gbp2, Irgm1, and Iigp1)." (PMID 32843537, 2020). "However, during multi-strain infection, both C4A and C4B were excluded from the salivary glands, while C4C and C4D replicated normally at this site." (PMID 23300458, 2013). "However, an OspC variant that does not bind human C4b still promotes bloodstream survival in mice, indicating that the role that OspC plays during mammalian infection remains incompletely understood." (PMID 32413091, 2020). "Moreover, PCM patients were shown to have a higher proportion of the non-expressed C4B allele, C4B*Q0, of deficient C4 isotypes, suggesting to the authors a possible influence of different C4 isotype and allotype frequencies in the course of infection." (PMID 33117339, 2020). "In addition, we classified the patients into subgroups based on the infection with DENV-1 or DENV-2 and compared the levels of C2, C4b, C5, C5a, C9, factor D and factor I between these classified groups." (PMID 32913345, 2020). "Capsid-deposited C4b neutralizes infection independent of C2 and C3 but requires C1q antibody engagement." (PMID 30926239, 2019). "Failure to detect C4A and C4B at this site was not simply due to mixed infection per se, as both these strains were able to disseminate to, and replicate within, the salivary gland when administered together." (PMID 23300458, 2013). "Deletion of Bmal1 in primary Bmal1fl/fl neuron cultures via infection with an AAV8-Cre viral vector (versus AAV8-eGFP control) suppressed the BMAL1 transcriptional target Nr1d1 (which encodes REV-ERBα) by 85% and induced C4b expression but caused no increase in C3." (PMID 33258449, 2020). "In particular, some genes involved in immune/inflammatory responses and infection (e.g., IL19, MAPK15, and SERPINB10) and components of a complement system (e.g., C4B, VTN, BDKRB1, and C4BPA) have not been previously reported regarding their expression and functions in human omental adipose tissue." (PMID 30816281, 2019).
cancer (17 papers, 2007 to 2025). A tumor composed of atypical neoplastic, often pleomorphic cells that invade other tissues. "When the complement cascade is strongly activated, the complement components C4b and C3b bind to mCRPs and inactivate them, but low levels of complement depositions are incapable of neutralizing sufficient percentages of the expressed mCRPs on the surface of the cancer cells." (PMID 17623109, 2007). "Meanwhile, CD55 and CD46 on malignant cells restrict deposited C4b and C3b, and CD59 inhibits complement membrane attack complex formation, therein protecting cancer cells from membrane damage." (PMID 17623109, 2007). "Volcano plot showed significantly upregulated transcripts of transmembrane 4 L6 family member 1 (TM4SF1), neuritin 1 (NRN1), MT2, mucin‐like protein 3 (MUCL3), complement component 4B (C4B) and insulin‐like growth factor‐binding protein 4 (IGFBP4) genes in treated KPC mice cancer cells." (PMID 38131168, 2023).
kidney disease (4 papers, 2021 to 2025). "Proteins CFB, С3, C4A, and C4B are associated with the development of kidney diseases." (PMID 39896931, 2024). "However, the effects of C4a and C4b on other types of kidney disease and kidney function have not been verified." (PMID 38898508, 2024).
cardiovascular disease (3 papers, 2014 to 2025). "Finally, another study investigated the interaction between smoking and a complement gene polymorphism (C4B*Q0, a silent allele of the C4B gene) in promoting cardiovascular disease morbidity and mortality." (PMID 40612949, 2025). "The low copy number of C4B is associated with cardiovascular disease (CVD) morbidity and mortality, as well as with the elevated ACTH-induced serum cortisol level, suggesting that some genetic variants of RCCX CNV, possibly c5 haplotypes, may directly influence the individual adaptation to stress." (PMID 25210767, 2014).
infectious disease (3 papers, 2008 to 2021). A disorder directly resulting from the presence and activity of a microbial, viral, or parasitic agent in humans. "Previous studies have demonstrated that complete or partial deficiencies of C4B are associated with susceptibility to infectious diseases." (PMID 32878183, 2020).
psychiatric disorder (3 papers, 2018 to 2023). A disorder characterized by behavioral and/or psychological abnormalities, often accompanied by physical symptoms. "Among genes mapped to loci shared between AN and psychiatric disorders, several immune-related genes were implicated, including the C4A, C4B, NCAM1, HLA-B, HLA-C, and HLA-E genes." (PMID 37658054, 2023).
cardiac disease (1 paper, 2017). "In our results, the expression of complement component C4a, C4b and inflammation genes Ccl11, Ccl8 were up expressed in older CSCs, indicated that targeting the complement system for the management of cardiac disease maybe a new therapy tool." (PMID 27980224, 2017).
C4B also shares sentences with these, for which no sentence is quoted: Hypertension (4 papers); Sepsis (4); staphylococcus aureus infection (4); bacterial infections (3); prostate carcinoma (3); glioma (2); hematologic malignancies (2); myeloid neoplasm (2); neurologic disease (2); ovarian carcinoma (2); pertussis (2); small cell lung carcinoma (2); thyroid cancer (2); abortion (1); adolescent idiopathic scoliosis (1); Aicardi-Goutieres syndrome (1); allergic disease (1); allergic rhinitis (1); antiphospholipid syndrome (1); asthma (1); astrocytoma (1); autism spectrum disorder (1); autoimmune hemolytic anemia (1); autoimmune thrombocytopenia (1); Blindness (1); brain diseases (1); cardioembolic stroke (1); celiac disease (1); chronic obstructive pulmonary disease (1); chronic periodontitis (1).
A further 70 diseases each share a sentence with C4B in 1 paper.